NAIF1 (nuclear apoptosis inducing factor 1)
Description:
Induces apoptosis.
Synonyms: C9orf90; DKFZp762G199; bA379C10.2
Tractability: Antibody: its Gene Ontology location is reachable by antibodies, with high confidence. PROTAC: ubiquitination databases record sites on it.
Gene: Protein-coding gene on chromosome 9 (128,061,233 to 128,068,206, reverse strand). Ensembl gene ENSG00000171169.
Subcellular location: Nucleus
Subcellular location (Human Protein Atlas): Nucleoplasm; Cytosol; Plasma membrane
Gene Ontology:
Molecular function: protein binding
Biological process: negative regulation of cell growth; regulation of mitochondrial membrane permeability involved in apoptotic process
Cellular component: nucleoplasm; nucleus
Genetic constraint (gnomAD): Loss-of-function variants: 14 observed, 19.57 expected, observed/expected ratio (o/e) 0.72, 90% interval 0.47 to 1.12. The upper end of that interval is the gene's LOEUF score, 1.12, which puts it in group 4 of 6, group 1 being the genes least tolerant of losing a copy. Missense variants: 362 observed, 437.78 expected, observed/expected ratio (o/e) 0.83, 90% interval 0.76 to 0.9. Synonymous variants: 191 observed, 190.09 expected, observed/expected ratio (o/e) 1, 90% interval 0.89 to 1.13.
Homologues: Orthologues: chimpanzee NAIF1 (99% identical), macaque NAIF1 (99% identical), dog NAIF1 (97% identical), guinea pig NAIF1 (95% identical), rabbit NAIF1 (95% identical), rat Naif1 (95% identical), mouse Naif1 (94% identical), tropical clawed frog naif1 (64% identical), zebrafish naif1 (60% identical), Drosophila melanogaster CG10209 (17% identical).
Diseases named in the same sentence as NAIF1 in open-access papers:
NAIF1 is named in the same sentence as 7 diseases in open-access papers, as found by Europe PMC text mining. Sharing a sentence is not in itself a finding about the gene and the disease. The quoted sentences say what the papers report.
gastric cancer (3 papers, 2014 to 2023). A primary or metastatic malignant neoplasm involving the stomach. "Results from western blotting and reverse transcriptional PCR demonstrated that NAIF1 was minimally expressed in gastric cancer cells." (PMID 24926661, 2014). "In conclusion, we found NAIF1 was minimally expressed in gastric cancer cell lines, and confirmed that NAIF1 is a nuclear protein." (PMID 24926661, 2014). "We screened and identified proteins whose expression was altered due to overexpression of NAIF1 in the gastric cancer cell line MKN45 using comparative proteomic technology, and the results were further verified through real-time qPCR and western blotting." (PMID 24926661, 2014). "Both reverse transcriptional PCR and western blotting experiments demonstrated that NAIF1 was minimally expressed in gastric cancer cell lines, MKN45, BGC823, AGS, and SGC7901; whereas NAIF1 was easily detected when it was transfected into the cells (Figure." (PMID 24926661, 2014). "In addition, NAIF1 expression was higher in well-differentiated (P = 0.004) than in moderately- or poorly-differentiated gastric cancer." (PMID 24926661, 2014). "Moreover, we confirmed that NAIF1 is a nuclear protein in the gastric cancer cell lines MKN45 and BGC823." (PMID 24926661, 2014). "Our research provides evidence that elucidates the role of how NAIF1 functions in gastric cancer." (PMID 24926661, 2014). "Moreover, the expression of NAIF1 was significantly down-regulated in human gastric cancer tissues compared to adjacent normal tissues." (PMID 24926661, 2014). "The results of our study may lead to a better understanding of how NAIF1 works in inducing apoptosis and also may shed light on the diagnosis and therapy of gastric cancers in the future." (PMID 24926661, 2014). "The cell cycle profile of gastric cancer cells under the effect of NAIF1 was investigated next." (PMID 24926661, 2014). "Our results show that NAIF1 was minimally expressed in all the tested gastric cancer cell lines." (PMID 24926661, 2014). "The differentially expressed proteins identified here are related to various cellular programs involving cell cycle, apoptosis, and signal transduction regulation and suggest that NAIF1 may be a tumor suppressor in gastric cancer." (PMID 24926661, 2014). "In our opinion, TXNRD1 may participate in the suppression of gastric cancer genesis or the up-regulation of TXNRD1 may be an adaptive mechanism in response to oxidative stress generated by overexpression of NAIF1." (PMID 24926661, 2014). "The MAPK/ERK pathways have been shown to play a role in controlling gastric cancer cell migration and invasion induced by IL-22, PRL3, NAIF1, and CCDC134." (PMID 37817112, 2023). "Therefore, NAIF1 may have therapeutic potential in the diagnosis and treatment of gastric cancer." (PMID 24926661, 2014). "Next, a comparative proteomic approach was used to identify the differential expression of proteins between gastric cancer cell lines MKN45/NAIF1 (−) and MKN45/NAIF1 (+)." (PMID 24926661, 2014). "Our research found NAIF1 inhibits the expression of RNH1, which suggests that NAIF1 may collaborate with chemotherapy drugs in the clinical treatment of gastric cancer." (PMID 24926661, 2014). "The cell cycle profile of gastric cancer cell lines, BGC823 and MKN45 was also investigated, and our results demonstrated that overexpression of NAIF1 may induce cell cycle arrest at G1/S phase via altering the expression levels of cell cycle regulation proteins cyclinD1, cdc2 and p21." (PMID 24926661, 2014). "The protein expression profiles of the gastric cancer cell line, MKN45 with or without NAIF1 overexpression were analyzed and compared using 24 cm pH 3–10 NL range immobilized pH gradient (IPG) strips." (PMID 24926661, 2014).
Sepsis (1 paper, 2021). Sepsis is defined as life-threatening organ dysfunction caused by a dysregulated host response to infection. "Taken together, these studies support our finding that both Bnip3 and Naif1 are involved in EC death and permeability in sepsis." (PMID 34638535, 2021).
tumor (4 papers, 2012 to 2025). "Four out of twelve smaller segments, located on chromosome 6 and 9, were isolated independently from other genomic imbalanced regions, and at least one of these regions on 9q contains tumor-related genes (NAIF1 and CIZ1)." (PMID 22551002, 2012). "Naif1 can significantly inhibit the growth rate of tumor cells and induce apoptosis through Casp9." (PMID 40507874, 2025). "Moreover, miR-125A-5p down-regulation determines NAIF1 gene over expression which also was shown to suppress tumor development." (PMID 32102477, 2020).
cancer (2 papers, 2021 to 2022). A tumor composed of atypical neoplastic, often pleomorphic cells that invade other tissues. "Notably, Bnip3 (Bcl2 interacting protein 3) has been shown to regulate human microvascular EC death and overexpression of Naif1 (Nuclear apoptosis-inducing factor 1) has been reported to increase apoptosis of cancer cells." (PMID 34638535, 2021). "Evidence suggests that nuclear apoptosis-inducing factor 1 (NAIF1), a protein often downregulated or lost in cancer regulates cellular migration and invasion through the MAPK pathway." (PMID 35409206, 2022).
NAIF1 also shares sentences with these, for which no sentence is quoted: melanoma (1 paper); nasopharyngeal carcinoma (1); Parkinson disease (1).